HOXB5 (homeobox B5)
Diseases named in the same sentence as HOXB5 in open-access papers (continued):
Sharing a sentence is not in itself a finding about the gene and the disease.
cancer (continued). "Moreover, we screened the target genes of miR-665 and confirmed that miR-665 directly targets HOXB5, which functions as a transcription factor in several cancer types." (PMID 34497766, 2021). "There are some reports on the role of HOXB5 in cancer progression." (PMID 34440097, 2021). "Furthermore, miR-507 downregulation or HOXB5 upregulation eliminated the cancer-inhibiting effects of lncRNA PRRT3-AS1 depletion in NSCLC cells." (PMID 37304647, 2021). "HOXB5 is known to play an important role in several cancers." (PMID 34440097, 2021). "Inhibition of HOXB5 suppressed the oncogenic function of cancer cells." (PMID 22768238, 2012). "HOXB5 may also interact with other signaling pathways that are involved in cancer development." (PMID 37894282, 2023). "Several crucial transcription factors, including STAT3, HOXD9, and HOXB5, are known to bind to ANGPT2 promoter regions, thereby activating ANGPT2 expression and promoting malignant phenotypes in cancer cells 58-60." (PMID 39309430, 2024). "In particular, the cancer-derived lines all show higher expression of the HOXC genes and of HOXB5 and HOXB7, whilst WMPY-1 expresses HOX genes closer to the 5′ (posterior) end of each HOX cluster." (PMID 24499138, 2014). "The other HOX genes that are notably upregulated in SK-OV3 cells (but generally not OV-90 cells) have previously been shown to be upregulated in other cancers, including HOXA13, HOXB5, HOXB9 and HOXD9." (PMID 20219106, 2010). "Our data support the view that promoter hypermethylation is a common mechanism involved in ovarian carcinogenesis and four target genes, HOXA9, HOXB5, SCGB3A1, and CRABP1, novel to this cancer type are identified." (PMID 17623056, 2007). "The results showed that some HOX genes in pan-cancer had significant strong correlation (R≥0.8): HOXA9 with HOXA10, HOXB5 with HOXB6 and HOXB8, HOXB8 with HOXB6 and HOXB9, HOXB3 with HOXB4 and HOXB5 and HOXB6, HOXC8 with HOXC9, HOXC9 with HOXC10, HOXD10 with HOXD11." (PMID 39980564, 2025). "HOXB5 protein upregulates the expression of mesenchymal markers such as VIM, SNAI1, and SNAI2 and downregulates the expression of CDH1, to enhance the mesenchymal transition, motility, and migratory ability of cancer cells." (PMID 34617205, 2022). "Our research found that HOXB5 inhibited the key genes CCND1 and MYC in the Wnt/β-Catenin signaling pathway, inhibited the tumor's occurrence, and inhibited the classical cancer pathway RTK pathway to inhibit cancer and improve OS." (PMID 34306077, 2021). "HOXB5 is a member of the homeobox (HOX) gene B cluster and plays key roles in several cancers." (PMID 32382535, 2020). "Patients who did not respond to immunotherapy had cancer tissues with elevated BMP6 and FN1 expression, in contrast to those who responded, where CD274, HOXB5, and PPIL3 were more expressed." (PMID 40642086, 2025).
tumor (24 papers, 2007 to 2024). "In order to explore the mechanism underlying HOXB5-mediated HCC metastasis, a human tumor metastasis PCR array was applied to test the changes in mRNA profile induced by HOXB5 change." (PMID 33897880, 2021). "The positive HOXB5 expression was positively correlated with loss of tumor encapsulation, microvascular invasion, poorer differentiation and higher tumor-nodule-metastasis (TNM) stage." (PMID 33897880, 2021). "Furthermore, HOXB5 expression was strongly associated with tumor stage, tumor grade, and the overall survival." (PMID 37627900, 2023). "In addition, we demonstrated that overexpression of HOXB5 was associated with tumor size, tumor-nodule metastasis, TNM stage, and relatively unfavorable OS and DFS." (PMID 35847904, 2022). "Different from HOXB3, HOXB5 was negatively correlated with myeloid cell differentiation signaling, but promoted tumor aggression and progression of various tumors including AML." (PMID 38254070, 2024). "HOXB5 is involved in tumor metastasis mainly through inducing matrix metalloproteinase (MMP) production and facilitating epithelial-to-mesenchymal transition (EMT)." (PMID 35847904, 2022). "Elevated HOXB5 expression was positively correlated with tumor size, tumor-nodule metastasis, and TNM stage." (PMID 35847904, 2022). "Further experiments proved that miR-625 inactivated the Wnt/β-catenin pathway by targeting Homeobox B5 (HOXB5), thereby exerting a tumor suppressor effect in NSCLC." (PMID 35308517, 2022). "Compared with the isogenic controls, exogenous HOXB5 expression in Caco-2 cells significantly increased the growth of subcutaneous tumors in mice, while depletion of endogenous HOXB5 in SW620 cells dramatically decreased tumor growth." (PMID 33456563, 2021). "In contrast, tumor volumes were increased in the HOXB5 overexpression group, the SRSF1 overexpression group, the circATP5B knockdown combined with the HOXB5 overexpression group, and the miR-185-5p mimic combined with the HOXB5 overexpression group." (PMID 33858489, 2021). "To explore the mechanism by which HOXB5 promotes CRC metastasis, we profiled the expression of a series of metastasis-related genes in Caco-2 and the isogenic Caco-2-HOXB5 cells using a Tumor Metastasis RT2 Profiler PCR array." (PMID 33456563, 2021). "We found that the protein levels of HOXB5 in CRC tissues were significantly higher than in adjacent non-tumor tissues." (PMID 33456563, 2021). "Next, the mRNA levels of HOXB5 were analyzed by real-time PCR in 20 normal colon epithelial tissues and 120 paired adjacent non-tumor tissues and primary CRC tissues." (PMID 33456563, 2021). "The loss of tumor encapsulation, microvascular invasion, poor differentiation and a higher TNM stage was found in HCC tissues with elevated HOXB5 expression." (PMID 33897880, 2021). "Immunohistochemistry was performed to detect the effects of the SRSF1/circATP5B/miR-185-5p/HOXB5 axis on tumor tissues." (PMID 33858489, 2021). "We found 5 target gene candidates (Skp2, Psme3, Pik3cd, Klf4, and Hoxb5) that were consistently predicted by the three software and involved in tumor-related signaling pathway." (PMID 30967999, 2019). "The expression of HOXB5 was higher in HCC tissues than in their adjacent non-tumor tissues." (PMID 35847904, 2022). "Similarly, positive expression of HOXB5 indicated poor prognosis, and HCC tissues with positive HOXB5 expression was positively correlated with loss of tumor encapsulation, microvascular invasion, poor differentiation and higher TNM stage." (PMID 33897880, 2021). "We designed rescue experiments to determine whether lncRNA PRRT3-AS1 performed tumor-promoting actions in NSCLC cells by controlling the miR-507/HOXB5 axis." (PMID 37304647, 2021). "Through these additional analyses, we can confirm that Hoxa9 upregulation is essential for the leukaemic phenotype of BcorΔE9-10KrasG12D tumours, and Hoxa7 and Hoxb5 may also be important." (PMID 30902969, 2019).
tumor (continued). "With the exception of HOXB5, higher promoter methylation frequencies were found among tumours from patients with relatively early FIGO stages (I-II) than late stages, but reached statistical significance only for HOXA9 and SCGB3A1 (P = 0.002, P = 0.020, respectively)." (PMID 17623056, 2007). "To verify the expression status of HOXB5 in HCC, especially its important clinical implications, we identified the mRNA expression level of HOXB5 in 100 pairs of HCC tissues and adjacent non-tumor tissues." (PMID 35847904, 2022). "Upregulation of HOXB5 was found in human HCC, and was strongly correlated with HCC tumor size, tumor-nodule metastasis, TNM stage, and relatively unfavorable OS and DFS." (PMID 35847904, 2022). "The transcript levels of HOXB1, HOXA7, HOXB5, HOXD8, HOXB9, HOXA9, and HOXA11 were significantly lower in ccRCC tumor tissues compared to adjacent normal tissues, which was consistent in both TCGA and ICGC cohorts." (PMID 36387262, 2022). "In vivo tumorigenicity assays illustrated that HOXB5 upregulation increased tumor growth of PLC/PRF/5 cells, whereas HOXB5 knockdown impaired tumor growth of MHCC97H cells." (PMID 33897880, 2021). "We found that, in addition to interacting with CD2, CD58 was co-expressed and physically interacted with HOXB family genes (HOXB2, HOXB3, and HOXB5), AKAP12, CLIC1, CPNE3, etc., which were reported to be involved in tumor initiation and progression." (PMID 34193136, 2021). "To investigate the role of HOXB5 in CRC cell proliferation and tumor growth, we performed Cell Counting Kit-8 (CCK8) and colony formation assays to measure changes of cell proliferation after the manipulation of HOXB5 expression level." (PMID 33456563, 2021). "To address this question, we used IHC staining to analyze the expression of HOXB5, CXCR4 and ITGB3 in primary tumor tissues and adjacent non-tumor tissues from two independent CRC patient cohorts." (PMID 33456563, 2021). "DNA hypermethylation of tumour suppressor genes seems to play an important role in ovarian carcinogenesis and HOXA9, HOXB5, SCGB3A1, and CRABP1 are identified as novel hypermethylated target genes in this tumour type." (PMID 17623056, 2007). "In line with this, our data also showed that HOXB5 promoted CRC proliferation and tumor growth." (PMID 33456563, 2021). "Furthermore, lncRNA PRRT3-AS1 and HOXB5 levels were reduced in tumor xenografts obtained from the sh-PRRT3-AS1 group, and lncRNA PRRT3-AS1-depleted tumor xenografts manifested clearly higher miR-507 levels." (PMID 37304647, 2021). "The positive correlation between HOXB5 expression and its target genes CXCR4 and ITGB3 in human CRC cell lines led us to explore whether it also existed in primary tumor tissues." (PMID 33456563, 2021). "In other studies, it was found that HOXB5 protein could bind with its cofactor PBX1 to induce apoptosis, thus delaying tumor progression." (PMID 34306077, 2021). "Moreover, overexpression of HOXB5 in HCC cells promoted the migration and infiltration of MDSCs to tumor sites through CXCL1-CXCR2 axis." (PMID 33897880, 2021).
adenocarcinoma (1 paper, 2009). A common cancer characterized by the presence of malignant glandular cells. "Another finding of our study was the remarkable regulation of hox genes in adenocarcinoma, for example Hoxa5, Hoxb5, Meis1 and Meis2." (PMID 19812696, 2009). "Furthermore some of the homeobox genes, e.g. Hoxa5, Hoxb5, Meis1 and Mrg1 were up to 9-fold repressed in adenocarcinomas." (PMID 19812696, 2009).
HOXB5 also shares sentences with these, for which no sentence is quoted: bladder (2 papers); gastric cancer (2); anencephaly (1); breast tumors (1); Burkitt lymphoma (1); congenital malformation (1); ependymoma (1); head and neck cancer (1); Hutchinson-Gilford progeria (1); immune dysfunction (1); ischemic stroke (1); lentivirus infection (1); leukocytosis (1); osteosarcoma (1); retinoblastoma (1); small cell carcinoma (1).